LINC00641 (long independently transcribed non-coding RNA 641)
Gene: Long non-coding RNA gene on chromosome 14 (21,200,079 to 21,206,900, reverse strand). Ensembl gene ENSG00000258441.
Diseases named in the same sentence as LINC00641 in open-access papers:
LINC00641 is named in the same sentence as 23 diseases in open-access papers, as found by Europe PMC text mining. Sharing a sentence is not in itself a finding about the gene and the disease. The quoted sentences say what the papers report.
glioma (12 papers, 2021 to 2024). A benign or malignant brain and spinal cord tumor that arises from glial cells (astrocytes, oligodendrocytes, ependymal cells). "Silencing NRGN expression can counteract the inhibition of glioma cell proliferation caused by upregulation of LINC00641." (PMID 38427106, 2024). "In comparison, the expression of LINC00641 was higher in glioma patients with lower grades, IDH mutation, 1p/19q codeletion and younger age." (PMID 35311131, 2022). "Low levels of LINC00641 expression were observed in glioma cell lines, consistent with our findings, and it intervened in glioma growth by the miR-4262/NRGN pathway." (PMID 38066643, 2023). "In glioma tissues, we found low levels of expression for LINC00641, AL139232.1, and AL691432.4, while high levels of expression were observed for AL390755.1, LEF1-AS1, and LYRM4-AS1." (PMID 38066643, 2023). "The expression levels of AC062021.1, SNHG6, LINC00507, FAM66C, DGCR10, and LINC00641 were significantly lower in glioma tissues than in normal brain tissues (P < .05) and gradually increased with the degree of malignancy." (PMID 37145002, 2023). "It has been reported that overexpression of LINC00641 in glioma can inhibit cell proliferation and promote cell apoptosis and achieved through LINC00641/Mir-4262/NRGN axis." (PMID 36033510, 2022). "We found that the expression of LINC00641 in glioma cells was significantly lower than that in normal astrocytes, and the expression of CRNDE and LNCTAM34a was significantly higher in glioma cells." (PMID 35311131, 2022). "Identical to our research, recent bioinformatics analysis reveals PWAR6 and LINC00641 are expression-dysregulated in glioma tissues." (PMID 33750353, 2021). "For LINC00641 in glioma, recent research suggested LINC00641 act as an inhibitor of glioma cell proliferation by targeting miR-4262/NRGN axis." (PMID 33750353, 2021). "In support of the tumor inhibition role of linc00641, another study showed that linc00641 suppressed the proliferation of glioma cells by targeting miR-4262 and upregulating NRGN." (PMID 33714199, 2021). "In contrast, LINC00641 exhibited the opposite results of CRNDE in glioma." (PMID 35311131, 2022). "According to recent studies, LINC00641 inhibits glioma cell growth." (PMID 35676651, 2022). "In our study, the expression of LINC00641 had a positive correlation with the OS of glioma patients, and the expression of LINC00641 was significantly higher in normal astrocytes than in glioma cells, which supported the idea that LINC00641 was a protective factor for glioma." (PMID 35311131, 2022). "Overexpression of LINC00641 in glioma cells inhibits cell proliferation and promotes apoptosis." (PMID 35155216, 2021). "LINC00641, as a tumor suppressor, offers new potential therapeutic targets for glioma patients by targeting the miR-4262/NRGN axis in glioma." (PMID 35620284, 2022). "A nine-EMT-related lncRNAs (HAR1A, LINC00641, LINC00900, MIR210HG, MIR22HG, PVT1, SLC25A21-AS1, SNAI3-AS1, and SNHG18) signature was identified in patients with glioma." (PMID 34288803, 2021). "In conclusion, LINC00641 competitively binds miR-4262 through the ceRNA mechanism to release NRGN, which plays an anti-tumor role in the progression of glioma, providing a new therapeutic target for glioma patients." (PMID 35155216, 2021). "Among the nine EMT-related lncRNAs identified in this study, LINC00900, MIR210HG, MIR22HG, PVT1, and SNHG18 were positively correlated with glioma malignancy, whereas HAR1A, LINC00641, SLC25A21-AS1, and SNAI3-AS1 were negatively correlated with glioma malignancy." (PMID 34288803, 2021).
gastric cancer (9 papers, 2020 to 2025). A primary or metastatic malignant neoplasm involving the stomach. "Because the role of linc00641 in gastric cancer is currently unclear, in the present investigation, we explored the underlying mechanism of linc00641 in gastric cancer." (PMID 33714199, 2021). "In this study, we found that LINC00641 was highly expressed in gastric carcinoma, and up-regulated expression of LINC00641 was associated with a poor prognosis in patients with gastric carcinoma." (PMID 32917936, 2020). "For example, LINC00641 was found to enhance the ability of cell growth and infiltration through sponging miR-340-5p in renal cell carcinoma, miR-429 in gastric cancer, and miR-378a in acute myeloid leukemia." (PMID 35756081, 2022). "LINC00641 was reported to be an oncogene in acute myeloid leukaemia, colorectal carcinoma and gastric carcinoma." (PMID 35311131, 2022). "We found that silencing linc00641 suppressed the viability and stimulated the apoptosis of gastric cancer cells, while linc00641 overexpression had the opposite effects." (PMID 33714199, 2021). "We found that linc00641 downregulation reduced wound closure in both gastric cancer cell lines, indicating that linc00641 regulates the migration of gastric cancer cells." (PMID 33714199, 2021). "In summary, linc00641 exerts its functions partly by targeting the miR-429/Notch-1 axis in gastric cancer." (PMID 33714199, 2021). "To further determine the role of linc00641 in gastric cancer cells, we used MTT assays to test the viability of MGC803 and SGC823 cells after linc00641 downregulation." (PMID 33714199, 2021). "The efficacy of linc00641 siRNA transfection was measured by real-time RT-PCR in both gastric cancer cell lines." (PMID 33714199, 2021). "We concluded that linc00641 promoted the malignant progression of gastric cancer by modulating the miR-429/Notch-1 axis." (PMID 33714199, 2021). "The efficacy of linc00641 overexpression in the gastric cancer cells was determined by real-time RT-PCR." (PMID 33714199, 2021). "Consistent with an oncogenic role of linc00641, its inhibition suppressed the viability of gastric cancer cells." (PMID 33714199, 2021). "Next, a Transwell assay was utilized to test the invasive ability of gastric cancer cells after linc00641 upregulation." (PMID 33714199, 2021). "We found that linc00641 promoted the malignant progression of gastric cancer cells by targeting miR-429 and increasing the expression of Notch-1." (PMID 33714199, 2021). "High expression of linc00641 was observed in gastric cancer specimens and was correlated with patient prognosis." (PMID 33714199, 2021). "Consistently, linc00641 overexpression repressed the expression of miR-429 in both gastric cancer cell lines." (PMID 33714199, 2021). "The results of the Transwell invasion assay demonstrated that linc00641 overexpression enhanced the ability of both types of gastric cancer cells to invade a Matrigel-coated membrane." (PMID 33714199, 2021). "We found that the linc00641 expression levels were decreased after the siRNA transfection of two gastric cancer cell lines." (PMID 33714199, 2021). "Downregulation of Notch-1 by siRNA transfection repressed gastric cancer cell viability and abolished the linc00641 overexpression-induced promotion of cell viability." (PMID 33714199, 2021). "The results of the MTT assays demonstrated that the downregulation of linc00641 reduced the viability of gastric cancer cells." (PMID 33714199, 2021). "To confirm the effects of linc00641 on cell migration, we conducted a wound healing assay after linc00641 overexpression in gastric cancer cells." (PMID 33714199, 2021). "Further experiments indicated that down-regulation of LINC00641 inhibited the autophagy process, making gastric cancer cells more sensitive to oxaliplatin." (PMID 32917936, 2020). "Inhibition of LINC00641 was observed to suppress cell viability and inhibit the autophagy process, which made gastric cancer cells more sensitive to L-OHP." (PMID 32917936, 2020).
gastric cancer (continued). "LINC00641 was highly expressed in 173 gastric cancer tissues compared with para-cancer tissues, and miR-582-5p expression was lower in cancer tissues." (PMID 32917936, 2020). "The expression of LINC00641 was higher in gastric cancer tissues; whereas miR-582-5p was down-regulated in gastric cancer tissues." (PMID 32917936, 2020). "Furthermore, gastric cancer patients with oxaliplatin resistance have higher levels of linc00641 expression." (PMID 33714199, 2021). "Moreover, a Transwell invasion assay was used to check the invasiveness of gastric cancer cells after linc00641 siRNA transfection." (PMID 33714199, 2021). "Moreover, linc00641 mediated the chemoresistance of oxaliplatin via the induction of autophagy by sponging miR-582-5p in gastric cancer." (PMID 33714199, 2021). "In conclusion, LINC00641 can function in gastric cancer by targeting miR-429/Notch-1 axis." (PMID 35155216, 2021). "Linc00641 plays a different role in gastric cancer cells than it does in other primary tumors." (PMID 33714199, 2021). "We observed that linc00641 downregulation suppressed the invasion of gastric cancer cells." (PMID 33714199, 2021). "In fact, the inhibition of linc00641 in both gastric cancer cell lines induced apoptosis." (PMID 33714199, 2021). "Since linc00641 was reported to regulate several miRNAs, including miR-197-3p, miR-424-5p, miR-194-5p, miR-4262, miR-378a in different types of cancers, it is necessary to investigate whether linc00641 targets these miRNAs in gastric cancer." (PMID 33714199, 2021). "Moreover, linc00641 sponged the expression of miR-429 and subsequently upregulated Notch-1 expression in gastric cancer cells." (PMID 33714199, 2021). "Therefore, the aim of our current study was to explore the molecular mechanism of linc00641 in gastric cancer." (PMID 33714199, 2021). "The expression of LINC00641 was also found to be high in gastric cancer." (PMID 33853611, 2021). "Because of the oncogenic functions of linc00641, targeting linc00641 could be useful to treat gastric cancer in clinical application in the future." (PMID 33714199, 2021). "Linc00641 upregulation attenuated gastric cancer cell apoptosis." (PMID 33714199, 2021). "We sought to determine whether the overexpression of linc00641 modulated the viability of gastric cancer cells." (PMID 33714199, 2021). "The results showed that linc00641 upregulation elevated the viability of gastric cancer cells." (PMID 33714199, 2021). "Taken together, these data indicate that linc00641 affects cell motility in gastric cancer." (PMID 33714199, 2021). "Thus, increased expression of linc00641 promoted the viability of gastric cancer cells." (PMID 33714199, 2021). "Linc00641 may have an oncogenic function in SGC7901 gastric cancer cells." (PMID 33714199, 2021). "We concluded that targeting linc00641 may be a therapeutic strategy for gastric cancer." (PMID 33714199, 2021). "Moreover, overexpression of linc00641 increased the expression of Notch-1 in gastric cancer cells." (PMID 33714199, 2021). "Hence, linc00641 downregulation promoted the induction of apoptosis of gastric cancer cells." (PMID 33714199, 2021). "Therefore, linc00641 performs its functions in gastric cancer in part via upregulation of Notch-1." (PMID 33714199, 2021). "However, the function of linc00641 and its underlying mechanism of action in gastric cancer have not been fully elucidated." (PMID 33714199, 2021). "Moreover, linc00641 can regulate the expression of miR-429 in gastric cancer." (PMID 33714199, 2021). "However, whether LINC00641 participates in the regulation of autophagy in gastric carcinoma is still unknown." (PMID 32917936, 2020). "This study found that PWAR6, LINC00641, SNHG14, and PART1 are markedly downregulated and involved in ferroptosis of gastric cancer." (PMID 36418919, 2022). "Thus, we tested whether linc00641 modulation could affect the apoptosis of gastric cancer cells." (PMID 33714199, 2021).
gastric cancer (continued). "LINC00641 have been shown to serve as important regulators in several cancers, including bladder cancer, NSCLC, gastric cancer, breast cancer and acute myeloid leukemia (AML)." (PMID 33853611, 2021). "In the present study, we found that LINC00641 was highly expressed in gastric adenocarcinoma and in L-OHP resistant gastric cancer cell lines." (PMID 32917936, 2020). "While established mechanisms of OXA resistance in gastric cancer involve JUNB-mediated MAPK hyperactivation, EphA2-induced EMT, METTL3-dependent DNA repair/stemness maintenance, and LINC00641-regulated autophagy, our study reveals a distinct immunosuppressive axis mediated by OASL." (PMID 41271618, 2025).
bladder cancer (8 papers, 2020 to 2023). "Downregulation of linc00641 was found in bladder cancer tissues, and it was associated with a poor prognosis." (PMID 33714199, 2021). "Most studies have indicated that lincRNAs and snoRNAs are upregulated in bladder cancer and associated with oncogenesis, progression and metastasis, although GAS-5, MEG3 and linc00641 were shown to be tumour suppressor genes and were downregulated in BLCA." (PMID 36831352, 2023). "An overexpression experiment also proved that linc00641 is a tumour suppressor gene in bladder cancer." (PMID 36831352, 2023). "Conversely, LINC00641 has been studied and reported as a tumor inhibitor in many cancers, including prostate cancer, bladder cancer, renal cancer, cervical cancer, non-small-cell lung cancer and breast cancer." (PMID 35311131, 2022). "Recent reports have revealed that the expression of LINC00641 was increased and involved in the tumorigenicity of bladder cancer, non-small-cell lung cancer (NSCLC) and acute myeloid leukemia (AML)." (PMID 33853611, 2021). "In vitro, the overexpression of LINC00641 reduced the proliferation, migration and invasion of bladder cancer cell lines." (PMID 35155216, 2021). "For example, linc00641 inhibited bladder cancer progression by targeting the miR-197-3p/KLF10/PTEN/PI3K/Akt cascade." (PMID 33714199, 2021). "The upregulation of linc00641 suppressed the proliferation, migration and invasion of bladder cancer cells and blocked tumor growth in vivo by interacting with miR-197-3p and targeting KLF10, leading to the inactivation of the PTEN/PI3K/Akt pathway." (PMID 33714199, 2021). "Linc00641 is located on 14q11.2 and is differentially expressed in a variety of cancers, such as non-small cell lung cancer, renal cell cancer, prostate cancer and bladder cancer." (PMID 36831352, 2023). "LINC00641/miR-197-3p/KLF10/PTEN/PI3K/AKT cascade may be a promising target for bladder cancer treatment." (PMID 35155216, 2021). "In general, LINC00641 is a tumor suppressor factor in bladder cancer." (PMID 35155216, 2021). "However, LINC00641 was downregulated in patients with bladder cancer and overexpression of LINC00641 markedly inhibited the proliferation, migration and invasion of bladder cancer cells." (PMID 33853611, 2021). "LINC00641 was reported as a tumor suppressor in bladder cancer via sponging miR-197." (PMID 32377223, 2020). "For example, the expression of lncRNAs such as TUC338 and PVT1 can be used as biomarkers for early diagnosis of bladder cancer, while the expression of PCAT6, NRON, GAS6-AS2, SNHG3, lncRNA TP73-AS1, and LINC00641 can predict poor prognosis of bladder cancer." (PMID 37592177, 2023). "However, it was shown that LINC00641 is a tumor suppressor in bladder cancer, as up-regulation of LINC0064 inhibited the progression of bladder cancer via the miR-197-3p/KLF10/PTEN/PI3K/AKT signal pathways." (PMID 32917936, 2020). "In conclusion, LINC00641 can competitively bind to miR-197-3p through the ceRNA mechanism to increase the expression of KLF10, further inhibit the activation of PTEN/PI3K/AKT pathway, and inhibit the proliferation, migration and invasion of bladder cancer cells." (PMID 35155216, 2021).
breast carcinoma (6 papers, 2020 to 2022). "In fact, in vitro overexpression of Linc00641 showed inhibition of breast cancer proliferation by preventing transition to the G1/S phase of the cell cycle, inhibition of migration and invasion in many cancer types, and induction of apoptosis." (PMID 36139687, 2022). "It is confirmed that miR-194-5p is a direct target of LINC00641 and the overexpression of miR-194-5p can reverse the inhibition of LINC00641 up-regulation on the biological behavior of breast cancer cells." (PMID 35155216, 2021). "Over expression of LINC00641 inhibits cell proliferation, migration, invasion and G1/S phase transition and promotes cell apoptosis in breast cancer cell lines." (PMID 35155216, 2021). "Mao analyzed the expression of LINC00641 in 166 breast cancer tissues, and statistical analysis showed that LINC00641 was significantly correlated with tumor size, lymph node metastasis and clinical stage (P < 0.01)." (PMID 35155216, 2021). "In breast cancer cell lines, overexpression of LINC00641 inhibits cell proliferation, migration and invasion, stagnates cells in G1 phase and promotes apoptosis." (PMID 35155216, 2021). "LINC00641 expression levels are decreased in breast cancer tissue, which is negatively correlated with tumor size, lymph node metastasis, and clinical stage." (PMID 34288803, 2021). "Additionally, LINC00641 has been shown to inhibit breast cancer cell proliferation, migration and invasion by sponging miR-194-5p." (PMID 35311131, 2022). "Moreover, in vivo studies revealed that Linc00641 overexpression notably reduces the tumor growth and the metastasis of breast cancer cells." (PMID 36139687, 2022). "As for breast cancer, the expression level of LINC00641 was negatively correlated with the size of tumor, lymph node metastasis, and clinical stage, which could restrain the proliferation and migration of breast cancer cells." (PMID 33330055, 2020). "Therefore, the molecular mechanism of LINC00641 overexpression inhibiting proliferation, migration and invasion of breast cancer cells can be elucidated through the sponge action of miR-194-5p, and LINC00641/miR-194-5p may contribute to the treatment of breast cancer as a favorable target." (PMID 35155216, 2021).
acute myeloid leukemia (5 papers, 2020 to 2022). Acute myeloid leukemia (AML) is a group of neoplasms arising from precursor cells committed to the myeloid cell-line differentiation. "When exploring the mechanism of LINC00641 in acute myeloid leukemia, LINC00641 was first located in the cytoplasm, and most LncRNAs in the cytoplasm were ceRNA mechanisms." (PMID 35155216, 2021). "Up-regulation of LINC00641 contributes to cell growth and migration in acute myeloid leukemia through modulation on miR-378a/ZBTB20 axis." (PMID 32297639, 2020). "In conclusion, LINC00641 acts through miR-378a/ZBTB20 signaling pathway and is expected to become a therapeutic target for acute myeloid leukemia." (PMID 35155216, 2021).
non-small cell lung carcinoma (4 papers, 2020 to 2022). A group of at least three distinct histological types of lung cancer, including non-small cell squamous cell carcinoma, adenocarcinoma, and large cell carcinoma. "Latest studies have clarified that LINC00641 is implicated in the tumorigenicity of bladder cancer, non-small cell lung cancer (NSCLC) and acute myeloid leukemia." (PMID 35266447, 2022). "In non-small cell lung cancer cell lines, overexpression of LINC00641 reduces the ability of proliferation and migration and increases apoptosis." (PMID 35155216, 2021). "LINC00641 is one member of lncRNAs, which has been found to play a role in modulating the proliferation and apoptosis of non-small cell lung cancer cells (NSCLC)." (PMID 32714145, 2020). "Therefore, LINC00641 as a tumor suppressor may play a role in the treatment of non-small cell lung cancer." (PMID 35155216, 2021).